CD68 (CD68 molecule)
Diseases named in the same sentence as CD68 in open-access papers (continued):
Sharing a sentence is not in itself a finding about the gene and the disease.
gastric tumor (6 papers, 2013 to 2022). "Analysis of the CICs in stomach tumors identified four subtypes of structures, with two of them CD68− in outer cells, which are usually E-cadherin+ tumor cells; and two are CD68+ in outer cells, suggesting macrophage-mediated engulfment." (PMID 26109430, 2015). "Furthermore, to detect the relevance of monocytes or macrophages and CD47 in vivo, Alexa Fluor®594 anti-CD68 antibody and HE staining was performed to detect macrophages in the gastric tumour xenograft model." (PMID 35694254, 2022). "To examine whether other immune cells such as myeloid–derived suppressor cells (MDSCs) and macrophages were also IL-6–positive cell population in the gastric tumor stroma, we performed an immunohistochemical analysis of CD11b and CD68 in the same samples." (PMID 23593346, 2013). "To shed light on myeloid populations present in gastric tumors, we re-clustered the 10,546 myeloid cells in our dataset and identified fifteen subclusters which were subsequently determined to be either macrophages (CD68, CD14), dendritic cells (FLT3, FCER1A), or neutrophils (CSF3R)." (PMID 36550535, 2022). "Immunohistochemical staining for CD68 (pan-macrophage), CD163 (M2-like macrophage), and H. pylori in 200 samples (100 cases of cardia-GC [CGC] and 100 cases of non-cardia GC [NCGC]) was performed." (PMID 34926251, 2021). "Based on these data and the role of immune cells in inflammation we next stained the tissues with the macrophage marker CD68 to measure levels of infiltrating macrophages in gastric tumor negative or positive for DUOX2 expression." (PMID 34439340, 2021).
glomerulonephritis (6 papers, 2015 to 2024). A renal disorder characterized by damage in the glomeruli. "Previous studies have found that there are more CD68+ macrophages infiltrating glomerulonephritis with Baumann's capsule breaks than there are in the glomerulus without such breaches." (PMID 39494325, 2024). "In the glomerulonephritis rats, the mRNA levels of CD68 and CCL2 in the kidney cortex were significantly increased at necropsy and significantly suppressed by repeated administration of PQ529 in a dose-dependent manner." (PMID 33159802, 2021). "In a previous report, we reported that administration of an Ang II receptor blocker to rats, a model of crescent-forming glomerulonephritis inducing CD68-positive macrophages and crescent formation following MCP-1 production, attenuated the progression of crescentic glomerulonephritis." (PMID 37231123, 2023). "Real-time PCR analysis of whole kidneys identified a marked increase in the gene expression of leukocyte markers (CD68, CD3e), proinflammatory cytokines (TNF-α, IFN-γ, CCL2) and macrophage elastase (MMP-12) in untreated and vehicle-treated mice at day 15 of glomerulonephritis." (PMID 26700873, 2015).
Hemophagocytosis (6 papers, 2019 to 2024). Phagocytosis by macrophages of erythrocytes, leukocytes, platelets, and their precursors in bone marrow and other tissues. "Immunohistochemistry showed numerous CD68 positive macrophages, which, on HE staining, presented clear signs of hemophagocytosis." (PMID 31887162, 2019). "In primary, pediatric forms of HLH, liver histopathology shows a characteristic pattern with a portal and sinusoidal infiltrate of CD3+, CD8+, granzyme B+ lymphocytes admixed with CD68+, CD1a- (benign but activated) histiocytes that exhibit hemophagocytosis." (PMID 31887162, 2019). "However, other histological abnormalities were still present, albeit less severe than in Pld3−/−Pld4−/− mice, including infiltrates of CD68+ myeloid cells, hepatomegaly, multifocal medullary hematopoiesis, and hemophagocytosis." (PMID 34620855, 2021). "However, numerous CD68-positive cells were observed at immunohistochemistry, while electron microscopy examination confirmed the presence of histiocytes and a characteristic feature of hemophagocytosis." (PMID 36275824, 2022). "Signs of hemophagocytosis were evident in 7 of 8 cases (P1, P2, P4, P5, P6, P7, P8), with emperipolesis and PAS-positive macrophages in the bone marrow, and highlighted by immunohistochemistry of CD68 (PG-M1) (DAKO, Code-Nr." (PMID 33471172, 2021). "Consequently, the number of CD68 positive cells does not seem useful to demonstrate liver involvement in hemophagocytosis, which relies mostly on haematoxylin and eosin." (PMID 31887162, 2019).
invasive carcinoma (6 papers, 2016 to 2025). A carcinoma that is not confined to the epithelium, and has spread to the surrounding stroma. "Moreover, a study by Hussein and Hassan (2006) clearly showed an increase in CD68+ myeloid cells in both the parenchyma and the stroma when going from normal breast tissue, to ductal carcinoma in situ, to invasive carcinoma." (PMID 39246414, 2024).
malaria (6 papers, 2011 to 2026). Malaria is a serious and sometimes fatal disease caused by a parasite that commonly infects a certain type of mosquito which feeds on humans. "Peptide P39 binds CD68, inhibiting sporozoite entry, offering a potential malaria treatment strategy." (PMID 40809316, 2025). "The data suggested that CD68+-Gal-9+ and CD68+-Tim-3+ macrophages play a role in the inflammatory response in liver during the erythrocytic stage of malaria." (PMID 34899708, 2021). "Ninety three placentae were investigated for malaria histological changes and immunohistochemical study for monocytes and macrophages (CD68)." (PMID 21929772, 2011). "However, both malaria groups showed significantly higher CD68 positive cells compared to the control group (3.58 ± 0.99/HPF, p < 0.05)." (PMID 32414377, 2020). "In the present study, we identified monocytes and macrophages in the placenta immunohistochemically, using monoclonal antibodies to CD68, in samples from women in Gadarif hospital which is located in an area characterized by unstable malaria transmission in eastern Sudan." (PMID 21929772, 2011). "Furthermore we introduce the presence/absence of CD68 cells as another way of stratifying the data; it is not clear what finding these cells in low numbers means (the normal number of these cells is not known), especially in the absence of malaria." (PMID 21929772, 2011). "Furthermore, a positive correlation was found between bronchial IL-33 expression and the number of CD68 + monocytes and neutrophils, septal congestion score, WBC score, and hyaline membrane formation score, suggesting IL-33 may play-role in lung destruction in severe malaria." (PMID 26437894, 2015). "Although this study demonstrated a similar range of leukocyte sub-sets (CD3, CD8, CD68, and neutrophil) among PE, non-PE and healthy subjects, the total score of WBC accumulation was significantly higher in severe malaria patients compared to normal cases." (PMID 26437894, 2015).
malignant fibrous histiocytoma (6 papers, 2014 to 2023). "For the differential diagnosis of various mononuclear histiocytic‐derived tumors or malignant fibrous histiocytoma, tumor cells were detected with negative or no dominant staining of CD68, a macrophage marker." (PMID 36052737, 2022). "Benign fibrous histiocytoma or low-grade malignant fibrous histiocytoma cells stain negative for S-100, CD34, and EMA, and stain positive for CD68." (PMID 24410763, 2014).
metastasis (6 papers, 2019 to 2024). The spread or migration of cancer cells from one part of the body (where they first appeared) to another. "Using univariate analysis for survival in the subgroup of tumour diameter ≥ 5 cm and lymph node metastasis subgroup, CD68+-TAMs and TNM stage were correlated with the prognosis of GC patients within these two subgroups." (PMID 32765828, 2020). "Correlation between clinical characteristics and status of CD68, CD163, and SOCS3 in lung metastasis." (PMID 37025997, 2023). "According to our meta-analysis results, we found that a high density of both CD68- and CD163-positive macrophages was significantly associated with high Ki67 expression, advanced histological stage, low HR expression and short OS, but not with tumor size, lymph node metastasis and HER2 expression." (PMID 31528210, 2019).
myeloid sarcoma (6 papers, 2016 to 2025). A tumor mass composed of myeloblasts or immature myeloid cells. "CD34, MPO, CD117, CD68, and lysozyme positivity also support the diagnosis of myeloid sarcoma." (PMID 33432557, 2021). "MPO, CD117, CD68 positive cells in lymph nodes indicated co-existing myeloid sarcoma." (PMID 33327223, 2020). "Immunophenotyping for monocytic markers, such as CD68, CD163, and MPO, can distinguish CNS chloroma from other neoplastic or inflammatory processes." (PMID 40951121, 2025). "Flow cytometry showed an immature cell population (CD45 dim) that was negative for CD34, CD56, CD117, and MPO; strongly positive for CD4; and variably positive for CD10, CD33, HLA‐DR, CD68, CD123, and E‐cadherin, consistent with myeloid sarcoma (MS)." (PMID 31788302, 2019).
Myocardial fibrosis (6 papers, 2016 to 2023). "A total of 56 days after BDL, myocardial fibrosis was seen (Pd56 < 0.001) accompanied by macrophage infiltration (CD68: Pgroup < 0.001) and systemic inflammation (TNFα: Pgroup < 0.001, white blood cell count: Pgroup < 0.001)." (PMID 37175858, 2023). "Under histological examination, we can observe infiltration of CD8+ T-cells, CD68+ macrophages, and signs of myocardial fibrosis." (PMID 36079112, 2022). "EET-B treatment significantly reduced myocardial fibrosis and CD68 positive area to 37.2±1.9% and 1.77±0.11%, respectively." (PMID 30979784, 2019). "Histologically, myocardial fibrosis peaked at day 21, and had decreased by day 35, but remained still higher than baseline values from day 0 (CD68 and SiriusRed)." (PMID 27084492, 2016).
ovarian tumor (6 papers, 2013 to 2024). "In ovarian tumors, the number of CD68+, CD163+ TAMs is reported to show a stepwise increase from benign, borderline to malignant." (PMID 25499804, 2014). "Late-stage human ovarian tumor biopsies contained primarily CD8+/CD45RO+ T cells and CD68+ macrophages, while NK and B cells occurred in the lowest numbers." (PMID 24040191, 2013). "The analysis of CD11c+, BDCA2+, and CD68+ cells suggests that myeloid DC, plasmacytoid DC and macrophages together constitute less than a total of 5% of each of the CD4+ and CD8+ cells in ovarian tumors." (PMID 24244610, 2013). "Immunofluorescence assays identified EOC ascites spheroids as multicellular structures containing ovarian tumor cells (PAX8+Ki67+) and numerous lymphocytes, such as TAMs (CD68+CD206+, CD68+CD86+), T cells (CD8+), DCs (CD11c+) and NK cells (CD56dim, CD56bright)." (PMID 39198883, 2024). "Overall, we found that neither ovarian tumor densities of ov-CD68+ or CD163+ ov-TAMs nor the ratio of ovarian CD68+/CD163+ ov-TAMs was significantly associated with patient OS or PFS." (PMID 34677277, 2021).
Parkinson disease (6 papers, 2015 to 2023). A progressive degenerative disorder of the central nervous system characterized by loss of dopamine producing neurons in the substantia nigra and the presence of Lewy bodies in the substantia nigra and locus coeruleus. "Thus, postmortem brain studies have revealed high levels of NOX2 in the substantia nigra of sporadic Parkinson's disease (PD) patients, localizing with the microglial marker CD68 as evidenced by immunostaining." (PMID 33953837, 2021). "Glial cells with excess amounts of neuroinflammatory markers (e.g., HLA-DR, CD68, and CD105) are abundant in neurodegenerative diseases such as Parkinson’s (PD) and Alzheimer’s (AD) diseases." (PMID 37446105, 2023).
pneumonia (6 papers, 2007 to 2025). An acute, acute and chronic, or chronic inflammation focally or diffusely affecting the lung parenchyma, caused by an infection in one or both of the lungs (by bacteria, viruses, fungi, or mycoplasma.). "The activation of CD68+/CD163+ macrophages could cause cell damage at an early stage of pneumonia development, and subsequently cause fibrotic changes in lung tissue." (PMID 37109672, 2023). "An increased number or activation of CD68-positive macrophages can indicate inflammation or tissue remodeling, for instance in conditions such as pneumonia, interstitial lung diseases, or chronic obstructive pulmonary disease (COPD)." (PMID 41009430, 2025). "As expected, areas of extensive pneumonia and oedema have a high density of CD68 expressing macrophages." (PMID 36717223, 2023). "No change in staining pattern was noted in the small airways or lung parenchyma of other lung diseases studied including, COPD, emphysema or pneumonia where significant NE and CD68 staining was noted." (PMID 17988392, 2007).
retinal degeneration (6 papers, 2017 to 2024). Degeneration of the retina. "An increase in CD68+ macrophages in the subretinal space have also been associated with ectopic RPE and RPE dystrophy in animal models of retinal degenerations, suggesting a role of CD68+ macrophages in the retinal inflammation commonly seen in retinopathies." (PMID 38904639, 2024). "Novel peaks were also seen at the Ccl3 and Ccl4 chemokine genes, as well as the interferon activated gene Ifi204 and the Cd68 surface marker —both of which were shown to become acutely accessible in a light damage model of retinal degeneration." (PMID 37880237, 2023). "CD68 has been extensively identified as a microglia activation markers in retinal degeneration studies." (PMID 36088481, 2022). "We found less microgliosis and lower expression of CD68 and IL-1β, which is in line with the published effects of minocycline in an ischemia-reperfusion model of retinal degeneration." (PMID 30042155, 2018). "CD68 is frequently used as a marker for reactive microglia in response to retinal degeneration." (PMID 32131893, 2020). "CD68, a marker of activated microglia, was co-stained with IBA1 during P7 to P28 in rd1 mice, while CD68 staining was absent at P56 and P180, suggesting microglia were activated at the early disease onset and turned still during later retinal degeneration progress." (PMID 28928639, 2017).
seminoma (6 papers, 2020 to 2026). A radiosensitive malignant germ cell tumor found in the testis (especially undescended), and extragonadal sites (anterior mediastinum and pineal gland). "As predicted from histological observations, transcripts encoding immune cell markers such as CD68, were generally higher in area 2 (ROIs 72–80), while the early germ cell and seminoma marker, KIT, was higher in section 1 (ROIs 81–91)." (PMID 40693358, 2026). "This study is the first to quantitatively and phenotypically characterize CD68+ and CD163+ tumor-associated macrophages (TAMs) in N0-stage seminomas at pT1 and pT2 stages." (PMID 40843751, 2025). "Median infiltration densities in seminoma also proved to be significantly higher for CD68+ macrophages, CD11c+ DCs, and CD20cy+ B cells compared to GCNIS, GCNIS + ly, and non-neoplastic samples." (PMID 38649788, 2024). "According to Kaplan–Meier survival analyses, over-expression of TYROBP and CD68 were significantly correlated with poor prognosis in seminoma (P < 0.05)." (PMID 33104706, 2020). "An initial H&E histochemistry and immunostaining of non‐seminoma (to detect OCT4 and CD68) of independent sections from each tumour sample was employed to ascertain their overall cellular composition." (PMID 40693358, 2026). "Comparative immunohistochemical analysis of CD68+ and CD163+ TAMs between pT1- and pT2-stage seminomas revealed pronounced interindividual variability, as reflected by the interquartile range (Q1–Q3) and visualized in the violin plot." (PMID 40843751, 2025). "A recent study demonstrated co-localization of the macrophage marker CD68 and the metalloproteinase MMP9 in seminomas." (PMID 39684459, 2024). "The univariate Cox proportional hazards regression analyses showed that CD68 and ITGAM were positively correlated with overall survival in seminoma." (PMID 33104706, 2020). "Three novel biomarkers, TYROBP, CD68 and ITGAM, were identified from databases and correlated with poor prognosis in patients with seminoma." (PMID 33104706, 2020). "The aim of the present study was to compare the quantity and spatial distribution of TAMs (CD68+/CD163+) in non-metastatic seminoma at the pT1 and pT2 stages in order to assess their potential association with tumor progression." (PMID 40843751, 2025). "In conclusion, our study demonstrated that TYROBP, CD68, and ITGAM could be regarded as prognostic biomarkers and therapeutic targets for seminoma patients." (PMID 33104706, 2020). "Ultimately, TYROBP, CD68, and ITGAM were considered three prognostic biomarkers in seminoma." (PMID 33104706, 2020). "In contrast, our study includes a substantially larger cohort of patients with non-metastatic seminoma and, for the first time, provides a comprehensive quantitative and phenotypic analysis of TAMs (CD68+/CD163+), including their spatial distribution across pT1 and pT2 stages." (PMID 40843751, 2025). "This study aimed to quantitatively and phenotypically characterize CD68+ and CD163+ TAMs in non-metastatic seminomas (pT1N0M0 and pT2N0M0)." (PMID 40843751, 2025).
thymoma (6 papers, 2014 to 2024). A neoplasm arising from the epithelial cells of the thymus. "In contrast, CD68 was significantly decreased (P < 0.001) in thymoma (THYM) compared with GTEx normal controls." (PMID 35550532, 2022). "Consistent with the TCGA thymoma dataset, a significantly higher proportion of patients with WHO type C or Masaoka stage III-IV thymoma had increased expression of CD68 and CCL18." (PMID 35675033, 2022). "Regarding the positivity for CD68, the thymoma and thymic carcinoma samples were categorized into two groups on the basis of the 1.31% cut-off point that indicates the median in normal thymic samples." (PMID 25499804, 2014). "A high percentage of CD68+ TAMs was observed in 43.8% (7/16) of thymic carcinoma samples and 30.2% (16/53) of thymoma samples (including 3 type A, 3 type AB, 5 type B1, 2 type B2 and 3 type B3), which were not statistically significantly different (p = 0.904)." (PMID 25499804, 2014). "The percentage of CD68+ TAMs varied from 0.13% to 7.54% with a median of 0.96% in thymoma samples, and 0.00% to 7.91% with a median of 1.08% in thymic carcinoma samples." (PMID 25499804, 2014). "The percentage of samples with a large number of CD68+ TAMs was not significantly different between thymic carcinoma and thymoma (7/16 versus 16/53, p = 0.904)." (PMID 25499804, 2014). "Although the percentage of CD68+ TAMs was not significantly different between thymoma and thymic carcinoma, in thymic carcinoma, which is associated with more frequent invasive growth and distant metastases, a higher percentage of CD163+ TAMs was found." (PMID 25499804, 2014).
abdominal aortic aneurysm (5 papers, 2015 to 2023). Enlargement and ballooning of the vessel that supplies arterial blood to the abdomen, pelvis and legs. "GRK2 expression positively correlates with myeloid- (CD68) and lymphoid-specific (CD3, CD4, and CD8) markers and with leptin in PVAT from patients with abdominal aortic aneurysms." (PMID 33020373, 2020). "Like the abdominal aortic aneurysm in the tunica intima, tunica media, and tunica adventitia of the thoracic aortic aneurysm, T cells (CD3) predominate among the inflammatory cells followed by macrophages (CD68)." (PMID 34656077, 2022).